IL13 (interleukin 13)
Diseases named in the same sentence as IL13 in open-access papers (continued):
Sharing a sentence is not in itself a finding about the gene and the disease.
Allergy (continued). "IL-4 and IL-13 secretion and subsequent binding to their receptor plays a major role in the development of the Th2 immune response and driving the pathogenesis of allergy." (PMID 40004029, 2025). "The IL-4/IL-13 pathways are involved in Th2 inflammatory responses and allergic reactions." (PMID 40607391, 2025). "IL-4 and IL-13 are involved in the inflammatory process of allergic reactions by regulating Th2 cell differentiation and stimulating IgE production by B cells, while IL-10 inhibits Th1 cell activation and proliferation, shifting the immune response to the Th2 type." (PMID 40038782, 2025). "Given that the levels of cytokines, including IL-4 and IL-13, are significant biological markers of allergic diseases like AD, our findings indicate that the pre-application of PPE led to a reduction in cytokine release and an improvement in the atopic damage observed in the goat AD model." (PMID 39943182, 2025). "Formal statistical analyses show that IL-6 rs1800795GG, IL-10RB rs2834167G positive genotypes, IL-13 rs1800925CC, CD23 rs2228137TT Klotho rs564481TT, might be risk factors for allergy." (PMID 39202464, 2024). "Previous study has suggested that HSP70 may exert protective effects in allergic diseases, such as downregulating eosinophilia, reducing Th2 cytokines (e.g., IL-4, IL-5, IL-13), and lowering allergen-specific IgE levels." (PMID 39640897, 2024). "IL-4, IL-5 and IL-13 are responsible for the production of non-opsonizing antibodies, allergic reactions, and the suppression of inflammatory reactions caused by Th1 cytokines." (PMID 38787374, 2024). "While IL-13 is recognized as an anti-inflammatory cytokine, IL-13 suggests its involvement in sensitization related to type 2 innate immunity in allergic diseases such as bronchial asthma, implying its essential role may vary depending on the disease." (PMID 38711706, 2024). "On the other hand, the type 2 cytokines IL-4 and IL-13 not only participate in the allergic inflammatory response, but also regulate the epithelial barrier in allergic diseases, resulting in a reduction in the expression of tight junction proteins in epithelial cells." (PMID 39388827, 2024). "Furthermore, 2LALERG® includes ULD of IL-4, IL-5, IL-6, and IL-13 to down-regulate the expression and/or secretion of these well-known allergy-related ILs." (PMID 36675006, 2023). "IL-4 and IL-13 are mainly involved in type 2 immunity and allergic diseases." (PMID 38074683, 2023). "IL13 is known as a mediator of a series of processes in allergic diseases, such as eosinophil chemotaxis, epithelial (goblet) cell proliferation, collagen deposition, and smooth muscle contractility, thus prompting us to evaluate these features in EoE esophagi." (PMID 36698146, 2023). "IL-13 is implicated in the alternative activation of macrophages resulting in a pro-reparative CD206+CD163+ macrophage subset that antagonizes IFN-γ inflammatory actions and is implicated in humoral immunity, allergies, and anti-parasitic responses." (PMID 36220814, 2022). "In addition, we observed evidence of intercellular communication via genes implicated in type 2 immunity (CCL11, CCL13, CD5L, IL4, IL5, IL13, IL24) and allergy-linked inflammation (CCL19)." (PMID 35483355, 2022). "IL-4 and IL-13 are more important for eliciting allergy than perhaps any other soluble factors." (PMID 36230993, 2022). "Similarly, CD8+ T lymphocytes, which produce the specific allergens IL-13 and IL-5, have been isolated in high numbers from skin lesions due to allergic reactions." (PMID 36275674, 2022). "A recent study showed that the clinical features of experimental atopic dermatitis are driven by IL-4 and IL-13 signaling via IL-4R and highlighted that IL-4R might serve as a potent therapeutic target for the treatment of AD and other allergic diseases." (PMID 35255962, 2022).
Allergy (continued). "The role of peroxisomes in MCs in regulating allergic disease remains unclear, however the impact of peroxisome defects on IL-13 production may also suggest that such organelle function could be targeted in the context of chronic allergic inflammation." (PMID 35756999, 2022). "In recent years, the role of IL13 in autoimmune and allergic diseases has been emphasized." (PMID 36143051, 2022). "IL-13 and IL-4 genes have been reported to play an important role in allergy." (PMID 34814942, 2021). "Besides their detrimental role in allergies, IL-4 and IL-13 also play important protective and immunoregulatory functions." (PMID 33976140, 2021). "After activation by basophils, ILC2s not only clearly accumulate but also enhance the expression of CCL11, IL-5, IL-9 and IL-13, which further leads to the accumulation of eosinophils and promotes other inflammatory responses in subjects with allergic diseases." (PMID 34177881, 2021). "A recent study of chronic rhinosinusitis, another allergic disease driven by IL-13, found that the nasal epithelium displayed basal cell hyperplasia where mucus secretory and ciliated cells got trapped in an undifferentiated state, resulting in reduced epithelial diversity." (PMID 33682796, 2021). "Moreover, recent studies have revealed that macrophages, especially alternatively activated macrophages (M2) induced by T helper 2 (Th2) cytokines, such as interleukin (IL)-4 and IL-13, participate in the pathogenesis of allergic diseases." (PMID 33662037, 2021). "In conclusion, in vivo described allergy-reducing DHA was found to lower OX40L surface expression, and both EPA and DHA lowered IL-12p40 and IL-23 production by DC2s in association with less IL-13 production by T-cells." (PMID 32431702, 2020). "In line with present observations, HDM/DNCB stimulation upregulated the T-bet, STAT3, and GATA3 and other allergy mediating cytokines (IL-4, IL-5, IL-10, IL-13, and IFN-γ) and chemokine (TARC) expression levels, while these were dose-dependently downregulated following SHE treatment." (PMID 32824648, 2020). "Another explanation is that IL17E, also known as IL25, could propagate production of IL-4 and IL-13 in different organs, which stimulate the expansion of eosinophils, and link between allergic disease and psoriatic disease." (PMID 32468320, 2020). "In line with the protective effects that were observed on acute allergic symptoms and IgE, histone acetylation of Th2-related genes (GATA3, IL-4, IL-5, and IL-13) of splenocyte-derived CD4+ T cells after allergy induction was lower in raw milk-treated mice than in shop milk-treated mice." (PMID 31349704, 2019). "However, PBMCs from allergy patients produce increased levels of Th2-type cytokines including IL-4, IL-5, and IL-13." (PMID 31826046, 2018). "Tissue hypereosinophilia occurs with increased IL-4, IL-5, and IL-13 production in B-cell lymphoma 6 (Bcl6)-knockout (KO) mice, suggesting that Bcl6 participates in allergy pathogenesis and that it may be important for reducing TH2 immune responses." (PMID 29696026, 2018). "Furthermore, allergy immunotherapy inhibited the increasing of IL-25 and Th2 cytokines IL-4, IL-5 and IL-13 with induction of CD4+CD25+ Foxp3+ Treg cells." (PMID 29784924, 2018). "In vitro, IL-13 can mediate the production of IgE and may play a key role in the pathogenesis of IgE-mediated allergic diseases." (PMID 29991953, 2018). "Targeting IL-13 in allergic diseases and dermatitis has already proven to be promising." (PMID 30460209, 2018). "The most recent work advances our understanding of the complex signaling pathways controlling allergic inflammation and paves the way for targeted manipulation of the IL-4/IL-13 pathway in the quest for additional therapeutic interventions against allergic diseases." (PMID 29868002, 2018).
Allergy (continued). "Alternative activation of macrophages due to Th2 responses (e.g., IL-4 and IL-13) has been shown to promote fungal persistence, allergy, and disease relapse, and neutralization of endogenous IL-4 has beneficial effects on the survival of mice systemically infected with C. albicans." (PMID 28119468, 2017). "In this review, it is argued that allergy represents an environmental risk factor for autism spectrum disorders, which involves a cascade of events including the Th2-cytokines IL4 and IL13, an M2A polarization of microglia, the release of growth factors, and the inhibition of autophagy in neurons." (PMID 29232822, 2017). "After characterizing the constructs, four different experimental conditions were analyzed in cryoprecipitate matrices: controls, air-lifted cultures (to increase cell stratification), partially desiccated cultures (to mimic dry eye disease), and IL-13-treated cultures (to mimic allergy)." (PMID 28248962, 2017). "For instance, in mice with allergen-induced airway hypersensitivity, huang qi injection suppressed the allergic reaction, enhanced interferon-gamma levels (important immune responsive cytokine) and decreased allergen-induced elevations of important allergy related interleukins IL-5 and IL-13." (PMID 29110710, 2017). "Furthermore, treating the conjunctival constructs with IL-13 mimics some of the responses found in allergic diseases." (PMID 28248962, 2017). "As expected, high serum levels of TH2 cytokines IL-5 and IL-13 were observed in the allergy model." (PMID 27445696, 2016). "In this regard, TH2 cell-derived cytokines such as IL-4, IL-5, and IL-13 play a critical role in the pathogenesis of allergic reaction; IL-4 and IL-13 stimulate IgE production, and IL-5 is responsible for eosinophil growth, differentiation, migration, activation, and survival." (PMID 27376063, 2016). "Both 1% GOS and budesonide significantly decreased the HDM allergy-induced increase in IL-13." (PMID 25849971, 2015). "In addition to histamine, conjunctival mast cells express and release the proinflammatory cytokines tumor necrosis factor (TNF)-α, interleukin-4 (IL-4), and IL-13 during acute allergic reactions." (PMID 23878502, 2013). "Control of maternal atopy in pregnancy and modulation of gene expression such as CTLA4 and IL13 may be a target for decreasing antenatal IgE production and possibly lowering perinatal allergy sensitization." (PMID 22481967, 2012). "Omega-3 PUFAs may alter the T helper cell balance by inhibiting interleukin-13 (IL-13) production, where IL-13 could be related to allergic diseases through its role in inducing IgE synthesis in B cells and Th2 type differentiation in T cells." (PMID 23049602, 2012). "Children sensitive to allergy showed 15% more IL-16, 32% more IL-13 and similar levels of IL-10." (PMID 20534153, 2010). "Thus, IL-13 is an immuno-regulatory cytokine, which is secreted primarily by Th2 type of helper T cells, and its major role has been shown to involve allergic diseases and immune responses against a number of parasites." (PMID 21162735, 2010). "IgE mediated allergy is promoted by T-helper (Th) 2 lymphocytes producing IL-4, IL-5 and IL-13." (PMID 19900263, 2009). "IL-4 may use its α- chain in the early and later stages when B cells are isotype-switched to secrete IgE, while IL-13 uses this receptor to promote the production and development of airway hyperresponsiveness and inflammation in the late stage of the allergic reaction." (PMID 40953067, 2025). "For example, arachidonic acid plays a crucial role in allergic diseases, as it generates leukotrienes and prostaglandins, such as prostaglandin E2, which can induce the production of Th2-type cytokines, such as IL-4, IL-5, and IL-13, as well as the synthesis of IgE." (PMID 38378549, 2024).
Allergy (continued). "The initial dose leading to a more Th1-dominant inflammatory response —the reduced expression of ACE2 in the cilia-bearing respiratory epithelia and IL-13-dependent Th2-inflammatory mechanisms in distinct IL-13-repsonsive respiratory epithelia cells in subjects with allergies —could play a role." (PMID 37997984, 2023). "IL-13 has been found to be significantly elevated in the serum and affected tissues of patients suffering from many autoimmune diseases including Sjögren’s syndrome, rheumatoid arthritis, and systemic sclerosis, and it plays a critical role in the progression of allergic diseases." (PMID 36670847, 2023). "Contrary to what might have been predicted by the Th1-Th2 cytokine shift paradigm, infections with helminths result in a Th2-polarized immune response including production of IL-4, IL-5, IL-13, eosinophilia, and high serum titers of IgE, all hallmarks of allergic disease." (PMID 35648372, 2023). "Thus, IL-13 also can promote B cells to produce IgE and contribute to the development of allergies." (PMID 36499702, 2022). "Indeed, studies continue to support basophils as key participants in IgE-mediated reactions, where they infiltrate inflammatory lesions, release pro-inflammatory mediators (histamine, leukotriene C4: LTC4) and regulatory cytokines (IL-4, IL-13) central to the pathogenesis of allergic diseases." (PMID 36578500, 2022). "Furthermore, the cytokines IL-4 and IL-13 can induce multiple fusogenic effects, which result in membrane fusion and giant cell formation and are responsible for the polarization of immunity towards Th2 response and IgE mediated allergy." (PMID 30941365, 2019). "Therefore, the inhibition of Dectin-2-mediated inflammation may provide a robust approach for treating allergic diseases by simultaneously reducing IL-5 and IL-13 production." (PMID 31861989, 2019). "Thus, it is necessary to understand the different signaling responses and downstream effects of these two cytokines to rationally design inhibitors of the IL-4- and/or IL-13-induced responses that could be used as therapeutics for asthma and allergies." (PMID 29868002, 2018). "Indeed, decreased IL-13 can be useful in the prevention of allergy, as stated for TGF-β2." (PMID 30150532, 2018). "The involvement of Th2 cells both helps to explain the joint involvement of IgE-producing B cells (via IL-4 and IL-13), mast cells (via IL-4 and IL-10), and eosinophils (via IL-5) in the allergic inflammatory process and accounts for the other pathophysiologic features of allergies." (PMID 24707309, 2014). "The involvement of Th2 cells both helps to explain the joint involvement of IgE-producing B cells (via IL-4 and IL-13), mast cells (via IL-4 and IL-10) and eosinophils (via IL-5) in the allergic inflammatory process and accounts for the other pathophysiologic features of allergy." (PMID 24624888, 2014). "In allergy-related cytokines, Fat only led to significant increases in multiple BALF cytokines, notably IL-4, IL-5, IL-6, IL-12, IL-13, IL-17, IL-33, TNF-α, and IFN-γ, compared to the normal chow group (NC) (all P < 0.05 or P < 0.01)." (PMID 40998975, 2025). "Analysis of the drug treatment groups revealed lower levels of serum total IgE, OVA-specific IgE, and Th2 cytokines, including IL-4, IL-5, IL-13, IFN-γ, and eosinophils, compared to the allergy group." (PMID 38396957, 2024). "Surfacen® inhibited Th2 inflammation by lowering levels of IL‐5 and IL‐13 and increasing INF‐γ in bronchoalveolar lavage, decrease of serum specific IgE, increase of IgG2a antibody, suggesting potential anti‐allergy effects towards Th1‐immune response." (PMID 39245804, 2024). "Damaged-epithelial cells-derived IL-25 and IL-33 rapidly induce secretion of IL-4 and IL-13 in ILC2 cells, indicating that ILC2 activation is induced in the early phase of allergy." (PMID 39567378, 2024).
Allergy (continued). "While allergic disease is predominated by T cell differentiation into Th2 cell response, Th1 cytokine, IFN‐γ, can also potentiate lung injury induced by Th2 cytokine IL‐13." (PMID 38923221, 2024). "Luteolin can inhibit the FcεRΙ- and MrGPrx2-mediated allergic reaction in vivo and in vitro, and reduce the serum levels of histamine, TNF-α, MCP-1, IL-8 and IL-13 in mice." (PMID 36611103, 2023). "They function mainly in the mediation of allergic disease, parasitic as well as helminthic infections, and participate in type 2 (TH2) inflammation that involves key cytokines such as IL-4, IL-5, and IL-13." (PMID 36832203, 2023). "In the allergy-induced group, the mRNA expression of IFN-γ and IL-12 was reduced, and the expression of IL-4 and IL-13 was significantly increased after treatment with anti-DNP IgE." (PMID 35889810, 2022). "The decrease in IL-13 in the rAmb a1-loaded PLGA-PEG nanoparticle treatment group also shows that the ratio of Th1/Th2 increases and the allergic reaction is reduced." (PMID 35163859, 2022). "Interleukin (IL)-4, IL-5, and IL-13, mainly secreted by TH2 cells, are the critical stimulus that promotes serum IgE production and are crucial players in the development of allergic disease and wheezing." (PMID 34631611, 2021). "The association between LPP and allergy may be mediated by an effect on the expression of BCL6 (B cell lymphoma 6), a transcription factor that represses the STAT6-mediated response to IL-4 and IL-13 and IgE class switching and inhibits Th2 cell differentiation in a mouse model." (PMID 32082391, 2020). "IL-13 is a key TH2 cytokine known to have functions in AHR and airway remodelling, among others, during allergy." (PMID 29728628, 2018). "In mouse and human allergies, IL-4 initiates TH2 responses and IgE isotype class switching, whereas IL-5 and IL-13 are important for eosinophil infiltration/activation and increased airway hyperreactivity in allergic asthma." (PMID 29696026, 2018). "The results support the concept that IL13 and HGF have protective effects and TGFβ2 may act as a risk factor, which may explain the diversity of results from epidemiological studies on the health-promoting effects of breastfeeding with regards to allergic diseases." (PMID 28538696, 2017). "Induction of allergy in the lungs via HDM resulted in an increase in mRNA for IL‐4, IL‐5, IL‐13 and IL‐17." (PMID 27059010, 2016). "Whether this reduction in IFN‐γ and IL‐13 producing CD1a‐reactive T cells is sustained beyond week 8 is unknown, however, it is noteworthy that it coincides with the induction of clinical tolerance, suggesting that wasp venom responsive CD1a‐reactive T cells may play a role in allergic disease." (PMID 26518614, 2016). "In splenocyte cultures, BM4 treatment led to the induction of the allergy-suppressing cytokines IL-10 and IFN-γ, accompanied by a suppression of IL-5 and IL-13 levels." (PMID 24175303, 2013). "Based on these results, to determine the effects of mapracorat on allergy-related cytokines, a combination of IL-4 plus TNF-α was selected for the HConEpiC, and IL-13 plus TNF-α was used for the HConF." (PMID 23878502, 2013). "The multiple linear regression analysis showed that after Derp 1 specific stimulation, allergy (R + AR) correlated positively with percentages of ICOS, IL-13 and IL-4-expressing T cells and negatively with CTLA-4 and IL-10-expressing T cells." (PMID 21356099, 2011). "The increase of TH2/TH1 ratio and the IL-5 and IL-13 levels in the BALF of rats that were sensitized with PCGs (GG and GP groups) suggest that the sensitization step was an important factor in the allergic reaction." (PMID 23283149, 2009). "If AA is a type I hypersensitivity allergic reaction, we would therefore expect that Th2 cells, eosinophils, basophils, IL-4, IL-5, IL-13, and IgE blood concentrations rise in APA, but not in AGA or the appendectomy negative group." (PMID 41596388, 2026).